HLA-G (major histocompatibility complex, class I, G)
Diseases named in the same sentence as HLA-G in open-access papers (continued):
Sharing a sentence is not in itself a finding about the gene and the disease.
cancer (continued). "As in cancers, HLA-G expression is upregulated in infectious diseases, in response to changes in the cytokine microenvironment, relating principally to increases in the levels of IL-10 and interferons." (PMID 24839609, 2014). "We here review the current data on the role of HLA-G in cancer based on recent findings of an unexpected antitumor activity of HLA-G in hematological malignancies." (PMID 24800261, 2014). "Among environmental factors able to reverse HLA-G repression, hypoxia, which is a common stress condition (cancer, transplantation, and pregnancy), is considered as a critical candidate." (PMID 24800261, 2014). "The idea that HLA-G might serve as a “public ligand” for NK inhibitory receptors thus set the stage for subsequent exploration of its role in cancer and infectious disease." (PMID 41445738, 2025). "Furthermore, intratumoral, intertumoral, and interpatient heterogeneity in HLA-G isoform expression has been frequently observed, including in CRC, raising concerns about the precision of HLA-G-targeted cancer immunotherapy." (PMID 41194925, 2025). "In this regard, in the context of precision medicine, our study highlights the need to explore the alternative splicing mechanisms involved in the regulation of HLA-G isoform expression and to perform HLA-G isoform typing for HLA-G-targeted cancer immunotherapy." (PMID 41194925, 2025). "In the context of precision medicine, our study also suggests that HLA-G isoform typing may be necessary for HLA-G-targeted cancer immunotherapy." (PMID 41194925, 2025). "Furthermore, heterogeneity of HLA-G isoform expression in cancer lesions is frequently observed, raising major concerns about the precision of HLA-G-targeted cancer immunotherapy." (PMID 41194925, 2025). "Moreover, blockade of HLA-G with specific antibodies and the development of anti-HLA-G chimeric antigen receptor (CAR) NK or CAR-T cells have demonstrated that HLA-G is a valid target for cancer immunotherapy." (PMID 41194925, 2025). "High expression of HLA-G is observed in immunosuppressive cancer patients with poor prognosis." (PMID 38877399, 2024). "HLA-G exhibits limited expression in normal tissues but is expressed in various types of human cancers, where it may play a role in immune system evasion." (PMID 39105878, 2024). "Over the years, many studies have shown HLA-G’s ectopic expression in various types of cancer." (PMID 38954689, 2024). "HLA-G function has also been reported to maintain tolerance in autoimmune and inflammatory diseases and post-transplantation, as well as mediate immune escape in cancer and infectious diseases." (PMID 39703498, 2024). "Additionally, previous studies have demonstrated that HLA-G can promote cancer metastasis by inducing angiogenesis." (PMID 38542078, 2024). "Furthermore, the opposite HRV correlations with sHLA-G levels in BC patients as compared to controls probably reflect the different roles of HLA-G in health and cancer." (PMID 39594832, 2024). "However, the expression of immunomodulatory molecules such as HLA-G by tumoral cells enables cancer to evade immune surveillance and the effector responses of the immune system against it." (PMID 39408976, 2024). "The use of antibodies, T cell engagers, CAR-T, and CAR NK cells for targeting the HLA-G pathway in cancer therapy could present both opportunities and challenges." (PMID 39766165, 2024). "This transformation occurs through the secretion of HLA‐G by the cancer cells." (PMID 39350478, 2024). "On this basis, blockade of HLA-G may be a superior partner to chemotherapy for long-term effective cancer control and reversal of drug-resistant tumors." (PMID 38310272, 2024). "The clinical importance of HLA-G as a potential agent in cancer drug discovery cannot be neglected." (PMID 38384647, 2024). "In addition, immune checkpoint, HLA-G of cancer cells can be targeted by CAR-NK to inhibit immunosuppression." (PMID 38726000, 2024).
cancer (continued). "Studies have reported the involvement of HLA-G in various cancers, including HCC." (PMID 39703498, 2024). "HLA-G, a non-classical class I HLA gene, has emerged as a potential marker for cancer susceptibility and prognosis due to its immunomodulatory properties." (PMID 39549048, 2024). "Similarly, the levels of CLU, which were reduced following the expression of HLA-G in the cancer cells, were found increased within the CRISPR/Cas9-mediated edited cells (left)." (PMID 39358558, 2024). "One of the molecules that may contribute to the development of cancer is the human leukocyte antigen G (HLA-G)." (PMID 38391781, 2024). "HLA-G is involved in a wide variety of processes, due to its tolerogenic functions such as maternal immune acceptance of the foetus, organ transplantation, viral infections, autoimmunity, and cancer progression." (PMID 39408976, 2024). "Cancer cells may upregulate expression of the human leukocyte antigen-G (HLA-G), which interacts with inhibitory receptors on immune cells, such as ILT2 and KIR2DL4, to suppress immune responses." (PMID 39040441, 2024). "In addition, we highlight the latest preclinical and clinical trial advances, with the aim of providing further insight into HLA-G-based modalities for cancer treatment and proposing new perspectives on targeted therapy for cancer patients." (PMID 38310272, 2024). "In various cancer types, there is significant aberrant induction of HLA-G expression." (PMID 38646539, 2024). "New immune checkpoints such as HLA-G and its receptors emerge as targets for cancer treatment." (PMID 39237366, 2024). "Conversely, higher HLA-G mRNA levels were found in patients with advanced stages of cancer." (PMID 39594832, 2024). "Indeed, the use of this method allowed reversing the induction mediated by HLA-G in these cancer cells." (PMID 39358558, 2024). "HLA-G is a physiology and pathologic immunomodulator detrimentally related to cancer." (PMID 37623251, 2023). "Recent studies demonstrated that an ectopic up-regulation of HLA-G in cancer cells may favor their escape from antitumor immune responses." (PMID 37573450, 2023). "This study confirmed that PD-1 and HLA-G and their receptors are closely related in cancer patients and that the high expression of these molecules may be predictive of a worse prognosis." (PMID 35328349, 2022). "Hence, in HCC, like in other cancers, expression of the tolerogenic HLA-G molecule correlates with a poor prognosis." (PMID 36311782, 2022). "HLA-G may have deleterious effects, promoting pathogen escape from immune system control (in cancers), or it may be beneficial (in septic shock), reflecting appropriate and effective feedback control of inflammatory processes." (PMID 35204759, 2022). "Soluble HLA-G (sHLA-G) in peripheral blood mainly includes sHLA-G1 and HLA-G5 isoforms, which maybe expressed and released by cancer cells in the tissue microenvironment." (PMID 36618382, 2022). "Furthermore, HLA-G can be expressed and secreted from non-cancer cells, such as human mesenchymal stem cells (hMSCs)." (PMID 35185904, 2022). "Microenvironmental factors such as non-classical human leukocyte antigen-G (HLA-G) have been associated with cancer invasiveness and metastatic progression." (PMID 36559230, 2022). "Moreover, since HLA-G possesses immune blocking functions, this also suggests that HLA-G can be involved as an immune checkpoint in the development of many cancers." (PMID 36253800, 2022). "HLA-G also potentiates the immune escape in cancer and infectious diseases." (PMID 35626255, 2022). "Of the HLA-G-positive patients, eight (47.1%) experienced cancer recurrence and 11 (64.7%) died." (PMID 35027037, 2022). "However, HLA-G neoexpression was detected under pathophysiological conditions, such as cancers, inflammatory diseases, auto-immune diseases and pathogen infections including viruses." (PMID 35237271, 2022).
cancer (continued). "Therefore, TET inhibitor can prevent aberrant HLA-G expression via maintenance of DNA methylation, which provides a novel potential target for cancer immunotherapy." (PMID 35185887, 2022). "In cancer, the expression of soluble and membrane HLA-G isotypes is a marker of a poor prognosis." (PMID 36032723, 2022). "All these findings indicated that the HLA-G expression in cancer microenvironment might be a key factor to investigate the progression of disease." (PMID 35185887, 2022). "Moreover, KIR2DL4 as a receptor on HLA-G, has been thought as one of potential targets for immunotherapy to treat cancer." (PMID 35345444, 2022). "In PTC, HLA-G expression gradually increased from hyperplasia to carcinomas." (PMID 36380313, 2022). "The fact that HLA-G is a crucial immunotolerance marker in cancer cell immune evasion is now largely accepted and is strongly related to progress of disease and prognosis for cancer patients." (PMID 33416081, 2021). "Through the study of the immune tolerance function of this gene in tumors, it is concluded that HLA-G is an effective immunosuppressive molecule, and eliminating the expression of HLA-G in cancer cells is of great significance for anticancer therapeutic effects." (PMID 35002537, 2021). "Importantly, hypoxia stress modulates the expression levels for important molecular targets in cancer immunotherapy including PD-L1, HLA-G, CD47, and VISTA." (PMID 33422072, 2021). "The expression of HLA-G in tissues may also be an important indicator for the prognosis of cancer patients." (PMID 34868081, 2021). "We speculate that an increase of cell surface expression of HLA-G on chemotherapy-treated cancer cells is mediated by downregulation of DMNT1 and epigenetic regulation of the TAP-1 promoter." (PMID 34663641, 2021). "The use of monoclonal antibodies against HLA-G in situations in which its expression is undesirable (for instance, in cancers and chronic viral disorders) would have many side effects since HLA-G is constitutively expressed in thymus, pancreas, and hematopoietic stem cells." (PMID 34845256, 2021). "The aim of this study was to identify the roles of HLA-G molecules across various types of cancer." (PMID 34276642, 2021). "HLA-G is yet another non-classical HLA class I member, whose expression is associated with a poor prognosis for patients with cancer, including patients with glioblastoma, colorectal and pancreatic cancer." (PMID 34335558, 2021). "Based on the current understanding of HLA-G and its various forms that have multiple immune tolerance regulating functions in malignant tumors, HLA-G is generally recognized as a biomarker that can be used to monitor the disease state and progression in cancer patients." (PMID 34868081, 2021). "In cancer, HLA-G expression can be involved in the evasion from anti-tumor immunity." (PMID 34948104, 2021). "The expression level of HLA-G has been demonstrated to be highly correlated with clinical parameters in many tumors, and its potential significance in the diagnosis and prognosis of cancer has been postulated." (PMID 34868081, 2021). "As HLA-G expression is specifically induced in most types of solid cancer cells, clinical benefits of HLA-G inhibitors could be expected for cancer immunotherapy." (PMID 34276691, 2021). "Additionally, particular attention is given to soluble HLA-G (sHLA-G) isoforms in NSCLC patients compared to other cancer types." (PMID 34361031, 2021). "The prognostic values of HLA-G varied greatly across cancers." (PMID 34276642, 2021). "Because of this tolerogenic role, HLA-G is involved in a wide variety of processes, such as maternal-fetal tolerance, organ transplantation, viral infections, autoimmunity, and cancer progression." (PMID 34557189, 2021). "Assuming the role the variants may have in HLA-G levels and cancer risk, the combination of the DEL and C alleles would pose the highest cancer risk." (PMID 34557189, 2021).
cancer (continued). "As a non-classic major histocompatibility complex (MHC) class I molecule, human leukocyte antigen G (HLA-G) is expressed in fetal-maternal interface and immunoprivileged site only in healthy condition, and in pathological conditions such as cancer, it can be de novo expressed." (PMID 34868081, 2021). "In most cancers, the expression of HLA-G is related to the patient’s poor clinical outcome." (PMID 34868081, 2021). "Human leukocyte antigen G (HLA-G) is known as a novel immune checkpoint molecule in cancer; thus, HLA-G and its receptors might be targets for immune checkpoint blockade in cancer immunotherapy." (PMID 34276642, 2021). "We conclude that non-classical HLA molecules are expressed in EwS under inflammatory conditions, but have limited functional impact on antigen-specific T cells, arguing against a relevant therapeutic benefit from combining CART therapy with HLA-G or HLA-E checkpoint blockade in this cancer." (PMID 34201079, 2021). "Abnormal expression of HLA-G plays a variety of roles in the progression of malignant tumors, such as inducing apoptosis, inhibiting immune cytolysis and cytotoxicity, and chemotaxis of regulatory cells and damage of different immune effector cells through receptor binding and/or trogocytosis." (PMID 34868081, 2021). "Thus, HLA-G and HLA-E are consistent features of EwS and are responsive to inflammatory stimuli in this cancer." (PMID 34201079, 2021). "This suggests that HLA-G expression plays different roles in distinct carcinoma types." (PMID 34361031, 2021). "HLA-G might therefore have a functional role in these carcinoma types and thus might act as an immune checkpoint molecule." (PMID 34361031, 2021). "It therefore remains uncertain what the exact role of HLA-G expression is in these carcinoma types." (PMID 34361031, 2021). "Additional studies should be performed to validate these preliminary findings and to conclude whether HLA-G plays a role in these carcinoma types." (PMID 34361031, 2021). "Due to its immune-inhibiting functions, HLA-G is often claimed as an immune checkpoint in cancer." (PMID 33213057, 2020). "The deleterious missense mutations determined in this inspection may have functional effects in HLA-G deregulation and may lead to pathological conditions like cancer." (PMID 32867672, 2020). "In addition, the studies in CRC and NSCLC patients analyzed the downstream pathways in cancer cells upon binding of HLA-G with the ILT4 receptor and showed increased phosphorylation of the ERK and AKT signaling pathways." (PMID 33213057, 2020). "However, HLA-G can be induced under pathological conditions such as viral diseases, inflammatory disorders, transplantation and cancer." (PMID 33505397, 2020). "As discussed in this review, HLA-G may be an important target for immune checkpoint inhibition in cancer." (PMID 33213057, 2020). "It has been demonstrated that HLA-G expression is crucial for the development of these cancers." (PMID 32922387, 2020). "However, the frequent neo-expression of HLA-G in many cancer types has been previously and extensively described and is correlated with a bad prognosis." (PMID 32922387, 2020). "Moreover, when we analyzed the interaction of the immune cells, there was less interaction found between immune cells and cancer cells in presence of HLA-G as well as PD-L1." (PMID 32961872, 2020). "Second, being the very limited size of the patients included, clinical significance of the heterogeneity of HLA-G and HLA-G isoform expression in cancers is still unknown." (PMID 33329527, 2020). "The results showed that HLA-G deregulation has distinct implications in different types of cancers." (PMID 32867672, 2020). "HLA-G expression may also be upregulated in several tissues under “pathological” conditions, such as cancer." (PMID 32184831, 2020).
cancer (continued). "Given HLA-G has been considered as an important immune checkpoint, intratumor heterogeneity of HLA-G expression, and different specificity of anti-HLA-G antibodies being used among studies, interpretation and clinical significance of HLA-G expression in cancers should be with caution." (PMID 33329527, 2020). "However, increased percentages of circulating and tissue infiltrating HLA-G positive immune cells occur in various pathological conditions like infections, cancers, transplants, and immune-mediated diseases." (PMID 32983083, 2020). "Finally, research gaps and future directions for HLA-G-based cancer immunotherapy are discussed and proposed." (PMID 33213057, 2020). "The Human Leukocyte Antigen G (HLA-G) is a protein-coding gene on chromosome 6p21.3 and has an important function in modulation of the immune responses and diseases such as chronic viral infections, autoimmune disorders, transplantation and cancers." (PMID 32867672, 2020). "However, HLA-G expression can be induced or up-regulated in pathological contexts like (i) cancer, (ii) auto-immune and inflammatory diseases, (iii) viral infections, and (iv) allo-transplantations." (PMID 32922387, 2020). "However, the weak in vivo effects of CREB on HLA-G expression as concluded from our data question any possible anti-cancer effects by CREB inhibition as a consequence of a down-regulated HLA-G transcription." (PMID 32993793, 2020). "It was proposed that HLA-G was necessary for cancer genesis given its pre-tumoral expression." (PMID 32922387, 2020). "HLA-G is highly expressed in cancers and creates immune-suppressive microenvironment." (PMID 32123232, 2020). "Hence, presence of HLA-G in-vitro, provided a better immune protective effect than PD-L1 to the cancer cells." (PMID 32961872, 2020). "However, HLA-G expression is often induced in pathological settings and is frequently seen in various cancers." (PMID 32560316, 2020). "Furthermore, human leucocyte antigen G (HLA‐G) (which plays a key role in regulating NK cell activity in pregnancy and cancer 31, 32) was also widely expressed." (PMID 31784984, 2020). "Many studies have claimed HLA-G as a new immune checkpoint in cancer." (PMID 32630545, 2020). "For instance, HLA-G and its soluble forms enable escape from host immune surveillance by inhibiting B cells, T cells, and natural killer cells and by inducing regulatory T cells, thereby mediating cancer invasiveness and metastatic progression." (PMID 31382533, 2019). "HLA-G is reportedly expressed in many types of cancer cells and involved in metastases." (PMID 31779209, 2019). "Human leucocyte antigen-G (HLA-G) plays an important role in the progression of human cancers." (PMID 30962267, 2019). "HLA-G expression is considered as an important immune escape mechanism of cancer cells." (PMID 30932005, 2019). "HLA-G (human leukocyte antigen-G) molecules could be a second important system of protection and survival both for initial embryos and cancer." (PMID 30899759, 2019). "As we did not observe such differences in HLA-G 3′UTR distribution, this may point to distinct contribution of HLA-G genotypes to the onset of specific forms of cancer or oncological phenotypes." (PMID 30932005, 2019). "Different degree of aberrant ectopic expression of HLA-G in cancers has been frequently found in most of the cancers studied so far, and the conception that HLA-G expression plays critical basically and clinical parts in cancer biology or therapy was established." (PMID 30234020, 2018). "Still, HLA-G upregulation may become relevant when attempting to target the cancer using adoptive transfer of T cells, NK cells or active immunization." (PMID 29464090, 2018). "In fact, HLA-G is considered as a target for cancer gene therapy." (PMID 30574154, 2018).